CERKL (CERK like autophagy regulator)
Diseases named in the same sentence as CERKL in open-access papers:
CERKL is named in the same sentence as 30 diseases in open-access papers, as found by Europe PMC text mining. Sharing a sentence is not in itself a finding about the gene and the disease. The quoted sentences say what the papers report.
retinal degeneration (12 papers, 2008 to 2024). Degeneration of the retina. "As CERKL is proposed as a resilience gene against oxidative stress in mammalian retina, and its depletion in KD/KO mice causes retinal degeneration, we investigated if KD/KO RPE suffered changes in the percentage of mono- and multinucleated cells." (PMID 34943121, 2021). "In contrast, CerKL knockdown causes retinal degeneration in zebrafish, with failure in the development of photoreceptor OS and increased apoptosis." (PMID 31244608, 2019). "In this paper we report the identification of a novel mutation in the CERKL gene (c.316C>A, p.R106S) that causes retinal degeneration in a large consanguineous family from Pakistan with 3 affected siblings." (PMID 18978954, 2008). "The finding that mutations in a CerKL gene are associated to a variant of autosomal recessive retinitis pigmentosa, and to Cone-rod dystrophy brought huge expectations to the field, as it associated sphingolipid metabolism and retinal degeneration." (PMID 31244608, 2019). "Its overexpression protects retinal cells from oxidative stress-induced death, whereas its downregulation renders cells sensitive to this damage; CerKL deficiency causes zebrafish retinal degeneration and photoreceptor apoptosis through increased oxidative damage." (PMID 31244608, 2019). "We identified a total of nine causal mutations, including six novel variants in RPE65, LCA5, USH2A, CNGB1, FAM161A, CERKL and GUCY2D as the underlying cause of inherited retinal degenerations in 13 of 26 pedigrees." (PMID 26352687, 2015). "Overall, we propose that this zebrafish model is a powerful tool to unveil CERKL contribution to human retinal degeneration." (PMID 23671706, 2013). "These high confidence variants were found in ABCA4, CERKL, MAK, PEX6 and RDH12 genes associated with retinal degeneration, that could be sufficient to cause pathology." (PMID 39365799, 2024). "Previous research reported that CERKL-knockdown zebrafish showed a retinal degeneration." (PMID 33152221, 2021). "Consistent with the phenotype observed in the cohort of patients analyzed in this study, the RPE65, LCA5, USH2A, CNGB1, FAM161A, CERKL and GUCY2D genes consisting mutations in 13 of the 26 pedigrees have been implicated in causing recessive non-syndromic retinal degeneration." (PMID 26352687, 2015). "This is the third reported mutation in CERKL causing retinal degeneration but is the first report to show that a single amino acid change in CERKL, rather than a null mutation, can cause retinal disease." (PMID 18978954, 2008). "Moreover, a missense mutation that alters NLS2 was identified in members of a Pakistani family affected with retinal degeneration, and it was suggested that a defective nucleocytoplasmic shuttling mechanism might be responsible for retinal degeneration in CERKL mutants." (PMID 21151604, 2010). "Thus the mechanism for triggering retinal degeneration in these patients could be the absence of nuclear localization and subsequent accumulation of mutant CERKL in the cytoplasm, which might be expected to trigger apoptotic cell death." (PMID 18978954, 2008).
retinitis pigmentosa (11 papers, 2009 to 2023). Retinitis pigmentosa (RP) is an inherited retinal dystrophy leading to progressive loss of the photoreceptors and retinal pigment epithelium and resulting in blindness usually after several decades. "For instance, mutations in the CERKL (ceramide-kinase like) gene, which normally protects cells from oxidative stress and apoptosis, can exacerbate oxidative stress in certain autosomal-recessive forms of retinitis pigmentosa." (PMID 38006824, 2023). "CERKL is a retinal resilience gene whose mutations underlie retinitis pigmentosa and cone-rod dystrophy, two retinal dystrophies characterized by progressive vision loss due to photoreceptor degeneration." (PMID 36232896, 2022). "To date, mutations in the CERKL gene have only been associated with retinal dystrophies, such as retinitis pigmentosa and cone-rod dystrophy, although recent studies have shown its potential role in other not-related-to-retina tissues and pathologies." (PMID 36232896, 2022). "The function of CERKL (CERamide Kinase Like), a causative gene of retinitis pigmentosa and cone-rod dystrophy, still awaits characterization." (PMID 24498393, 2014). "The Yakut cattle also had a signature of selection in the region of the keramide kinase like gene (CERKL) expressed in the retina, which possesses variants responsible for retinitis pigmentosa in humans, associated with light stress response and protection of photoreceptor cells." (PMID 30154520, 2018). "In retinitis pigmentosa, the implicated genes that appeared across multiple studies include MERTK, PDE6B, CERKL, and ABCA4." (PMID 36836473, 2023). "We report the characterization of 4 in-frame alternatively spliced isoforms of CERKL, which is responsible for an autosomal recessive form of retinitis pigmentosa (RP26)." (PMID 19158957, 2009). "The precise function of CERKL, a Retinitis Pigmentosa (RP) causative gene, is not yet fully understood." (PMID 34943121, 2021).
cone-rod dystrophy (9 papers, 2013 to 2023). Inherited retinal dystrophies that belong to the group of pigmentary retinopathies. "Mutations in the ceramide kinase-like (CERKL) gene have been reported to cause autosomal recessive RP and cone-rod dystrophy." (PMID 37569703, 2023). "In fact, patients carrying mutations in CERKL present early onset rod-cone dystrophy despite relatively preserved visual acuity and a very distinctive RPE phenotype, e.g., RPE granularity and frank macular RPE atrophy." (PMID 34943121, 2021). "Mutations in CERKL (CERamide Kinase Like) have been reported to cause non-syndromic autosomal recessive RP as well as cone-rod dystrophy (CRD)." (PMID 34943121, 2021). "Among them, CERKL (CERamide Kinase Like) was first identified in a RP Spanish family and later was shown to promote cone-rod dystrophy (CRD), a retinal disorder associated with a more severe phenotype." (PMID 24498393, 2014). "An alteration in OS phagocytosis in a zebrafish CerKL knockout suggests a role for CerKL in RPE cell phagocytosis, leading to rod-cone dystrophy." (PMID 31244608, 2019).
Retinal dystrophy (6 papers, 2013 to 2025). Retinal dystrophy is an abnormality of the retina associated with a hereditary process. "Mutations in the Ceramide Kinase-like (CERKL) gene cause retinal dystrophies, characterized by progressive degeneration of retinal neurons, which eventually lead to vision loss." (PMID 36232896, 2022). "CERKL was the most common gene implicated in a Tunisian population with retinal dystrophy, while RDH12 was also common in the Israeli population with inherited retinopathies." (PMID 33921607, 2021). "The clinical data of six patients from six unrelated families with a diagnosis of a retinal dystrophy and with at least two variants in CERKL were reviewed." (PMID 33322828, 2020). "Yet VA encompassed an incredibly broad range both at baseline and during follow-up, with over 50% of individuals above 40 years old still having no or mild visual impairment as per the WHO classification, indicating the variable prognosis associated with CERKL-retinal dystrophy." (PMID 37331655, 2023). "The phenotype of CERKL-retinal dystrophy is broad, encompassing isolated macular disease to severe retina-wide involvement, with a range of functional phenotypes, generally not fitting in the rod-cone/cone-rod dichotomy." (PMID 37331655, 2023). "Our findings highlight the role of CERKL, a retinal dystrophy gene, in the regulation of mitochondrial health and homeostasis in central nervous system anatomic structures other than the retina." (PMID 36232896, 2022). "We present a case series of six patients from six unrelated families diagnosed with inherited retinal dystrophies (IRD) and with two variants in CERKL recruited from a multi-ethnic British population." (PMID 33322828, 2020). "The human CERKL gene is responsible for common and severe forms of retinal dystrophies." (PMID 23671706, 2013).
autosomal recessive retinitis pigmentosa (2 papers, 2005 to 2020). Autosomal recessive retinitis pigmentosa (RP) is an autosomally recessive inherited retinal dystrophy leading to progressive loss of the photoreceptors and retinal pigment epithelium and resulting in blindness usually after several decades. "Autosomal recessive retinitis pigmentosa is caused by mutations in over 40 genes, one of which is the ceramide kinase-like gene (CERKL)." (PMID 33322828, 2020). "Recent reports that mutations in the related gene CERKL on chromosome 2q31 cause autosomal recessive retinitis pigmentosa (RP26) indicate a link of the ceramide kinase gene family to retinal neurodegeneration." (PMID 16225677, 2005).
neuroblastoma (2 papers, 2014 to 2022). Neuroblastoma (NB) is the most common solid, extracranial childhood tumor. "CERKL alleviated neuronal damage through activating mitophagy in a SIRT1/PINK1/Parkin-dependent pathway in human neuroblastoma cells." (PMID 36507335, 2022). "Furthermore, enhanced stability of SIRT1 by overexpression of Ceramide Kinase-Like Protein (CERKL) promoted the production of PINK1 and Parkin in human neuroblastoma cells of OGD/R." (PMID 36507335, 2022).
Retinal Disease (2 papers, 2008 to 2014). "This is the third reported case of CERKL gene mutations causing retinal disease and the first presenting a missense mutation, rather than a null allele." (PMID 18978954, 2008).
Blindness (1 paper, 2008). Blindness is the condition of lacking visual perception defined as a profound reduction in visual perception. "We therefore screened the DNA of one of the affected brothers (the proband) and a normal control individual for the 14 coding exons and splice site junctions of CERKL, the gene implicated in the RP26 form of inherited blindness." (PMID 18978954, 2008).
Chorioretinal atrophy (1 paper, 2023). Atrophy (wasting) of the choroid and retinal layers of the fundus. "Common retinal changes observed in CERKL-retinopathy include peripheral and macular circular areas of chorioretinal atrophy, little to no pigment deposits, and fine hyperautofluorescent macular dots." (PMID 37331655, 2023).
hearing loss (1 paper, 2026). "CERKL (Ceramide Kinase Like) mutations are associated with autosomal recessive RP and cone–rod dystrophy, while USH2A (Usherin) mutations cause both nonsyndromic RP and Usher syndrome type 2, which combines RP with hearing loss." (PMID 41562913, 2026).
Leber congenital amaurosis (1 paper, 2015). Leber congenital amaurosis (LCA) is a retinal dystrophy defined by blindness and responses to electrophysiological stimulation (Ganzfeld electroretinogram (ERG)) below threshold, associated with severe visual impairment within the first year of life. "For example, mutations in ABCA4, CRX, CERKL, PROM1, SEMA4A, GUCY2D can cause either CCRD, but also RP or Leber congenital amaurosis (LCA)." (PMID 26103963, 2015).
Macular dystrophy (1 paper, 2023). Macular dystrophy is a nonspecific term for retinal degeneration, generally confined to the macula, usually presumed of genetic origin. "CERKL-retinopathy has a broad phenotypic spectrum ranging from isolated macular dystrophy to severe generalized retinal involvement, and it often does not follow the classical RCD/CORD dichotomy." (PMID 37331655, 2023).
nyctalopia (1 paper, 2020). "A 30-year-old Pakistani female, homozygous for a c.1617-16_1630inv30 CERKL mutation, had symptoms of photopsia, photophobia, nyctalopia, abnormalities in her colour vision and central and peripheral visual field loss in her mid-twenties." (PMID 33322828, 2020). "A 58-year-old Indian male, homozygous for a c.1045_1046delAT, p.(Met349Valfs*20) mutation in CERKL, noted symptoms of nyctalopia and a slow gradual deterioration in vision in his teens, with a sharp deterioration in the last five years." (PMID 33322828, 2020). "A 56-year-old white Caucasian male, compound heterozygous for c.847C > T, p.(Arg283*) and c.566_569delinsGTG, p.(Lys189Serfs*5) CERKL mutations, first noticed symptoms of nyctalopia and visual loss aged 25 years." (PMID 33322828, 2020). "A 34-year-old white Caucasian male, homozygous for c.847C > T, p.(Arg283*) in CERKL, first noticed visual symptoms at the age of 25, reporting nyctalopia and difficulty with colour vision." (PMID 33322828, 2020).
pancreatic cancer (1 paper, 2025). "The results showed that, compared to the control group, more mice in the CERKL overexpression group showed more lung metastases, suggesting that CERKL promoted the migration and invasion of pancreatic cancer cells in vivo." (PMID 41288005, 2025). "In conclusion, CERKL promoted the migration and invasion of pancreatic cancer." (PMID 41288005, 2025). "Thus, CERKL promoted the migration and invasion of pancreatic cancer." (PMID 41288005, 2025).
Usher syndrome (1 paper, 2026). A syndromic diseae characterized by the association of sensorineural deafness (usually congenital) with retinitis pigmentosa and progressive vision loss. "CERKL mutations have been previously reported as significant causes of autosomal recessive RP in Middle Eastern populations, while USH2A represents one of the most common causes of Usher syndrome worldwide, suggesting that this gene may be particularly important in the Turkish RP population." (PMID 41562913, 2026).
retinopathy (9 papers, 2009 to 2023). "Other groups, however, report a higher prevalence of CERKL-associated retinopathy, accounting for 33% and 5% of autosomal recessive IRD in Yemenite Jewish and Spanish populations, respectively." (PMID 37331655, 2023). "One patient (ID, 30) was homozygous for a VUS and had a phenotype that matched CERKL-retinopathy; hence, he was included in the cohort and considered as a likely CERKL-associated case." (PMID 37331655, 2023). "This study aims to establish the phenotypic and genetic spectrum by examining the largest case series of CERKL-associated retinopathy patients to date, to better understand this disorder and to optimize future clinical management." (PMID 37331655, 2023). "This study examines the detailed clinical and functional phenotype in the largest cohort of genetically characterized patients with CERKL-associated retinopathy to date." (PMID 37331655, 2023). "The inherited retinopathies associated with the CERKL gene vary in age at presentation and in degree of severity, but generally are characterised by a central visual impairment early on." (PMID 33322828, 2020). "Early identification and diagnosis are important in the management of patients with CERKL-associated retinopathy, as it manifests more severely than most similarly appearing cone-rod and rod-cone dystrophies." (PMID 30696906, 2019). "The phenotype of CERKL-associated retinopathy has traditionally been classified clinically under the spectrum of arRP, RP26 (OMIM#608380)." (PMID 30696906, 2019). "This cross-sectional case series reports a novel phenotypic manifestation of CERKL-associated retinopathy." (PMID 30696906, 2019). "This study represents the largest series of patients with CERKL-associated retinopathy to date." (PMID 37331655, 2023). "Taken together, AF retinal imaging of CERKL-associated retinopathy reveals a unique phenotype which may assist specialists in arriving at an accurate diagnosis." (PMID 30696906, 2019). "Four cases of retinopathy caused by homozygous nonsense mutations in CERKL are presented." (PMID 30696906, 2019). "CERKL-retinopathy has been categorized to date as either presenting as RCD or CORD, even in patients with the same genotype, excluding possible genotype-phenotype correlations." (PMID 37331655, 2023). "In this context, the physiologic relevance of each CERKL isoform and their particular contribution to retinal disorders is yet to be determined." (PMID 19158957, 2009). "These are currently under investigation for other IRD genes such as ABCA4 and if successful, might also prove useful for CERKL retinopathy." (PMID 37331655, 2023). "Out of the remaining 60 patients, 7 patients (12%) revealed one potentially disease-causing variant in a gene causing recessive retinopathy in combination with a phenotype usually associated with mutations in the respective gene (ABCA4, n = 5; CDH3, n = 1; CERKL, n = 1)." (PMID 29555955, 2018). "Therefore, the identification of CERKL as an RP gene provided a missing link between alterations in SL metabolism to inheritable retinal disorders and suggested a new avenue for elucidating the ethiopathological mechanisms." (PMID 19158957, 2009).
cancer (2 papers, 2025). A tumor composed of atypical neoplastic, often pleomorphic cells that invade other tissues. "By enhancing resistance to oxidative stress, CERKL may contribute to the survival of cancer cells under hostile conditions, making it a potential target for therapies aimed at increasing cancer cell susceptibility to oxidative damage." (PMID 39925808, 2025). "CERKL signaling in cancer and paracancer tissues was found in both the nucleus and cytoplasm." (PMID 41288005, 2025). "CERKL could protect cancer cells from oxidative stress to maintain cellular homeostasis." (PMID 41288005, 2025). "CERKL could protect cancer cells from oxidative stress and promotes cancer progression." (PMID 41288005, 2025).
tumor (2 papers, 2016 to 2025). "L296V mutation enhances the tumor‐promoting effect of CERKL." (PMID 41288005, 2025). "L296V mutations strengthened the tumor‐promoting ability of CERKL." (PMID 41288005, 2025).
neurodegenerative disease (1 paper, 2022). A disorder of the central nervous system characterized by gradual and progressive loss of neural tissue and neurologic function. "Overall, in this work we determined that CERKL is not only involved in mitochondrial morphology and function in neurons, but also in mitochondrial trafficking regulation, contributing to the intricate network that regulates mitochondrial health in neurodegenerative diseases." (PMID 36232896, 2022).
CERKL also shares sentences with these, for which no sentence is quoted: helminthic infections (2 papers); infection (2); schistosomiasis (2); Bardet-Biedl syndrome (1); breast tumors (1); central serous chorioretinopathy (1); Cognitive impairment (1); COVID-19 (1); Photophobia (1); Stargardt disease (1); Usher syndrome type 2 (1).